BRAF (B-Raf proto-oncogene, serine/threonine kinase)
Diseases named in the same sentence as BRAF in open-access papers (continued):
Sharing a sentence is not in itself a finding about the gene and the disease.
cancer (continued). "Future research can explore the molecular mechanism of multiple primary cancers (such as the coexistence mode of RET/RAS/BRAF mutation) and evaluate the cost effectiveness of calcitonin screening to optimize clinical practice." (PMID 41261620, 2025). "The most frequent BRAF mutation is BRAF V600E, which leads to uncontrolled cell proliferation and cancer." (PMID 40860828, 2025). "Vitamin C has been shown to boost DNA demethylation in many cell lines, including BRAF-mutated cancer cell lines." (PMID 40102611, 2025). "Given the history that these drugs were both developed to treat cancers with BRAF V600 mutation and that combination treatment with inhibition of the PI3K-AKT pathway has been explored, we assumed that such background was reflected in these results." (PMID 40383732, 2025). "Given that oncogenic RAS mutations are upstream activators of RAF signaling and represent another major oncogenic driver in NSCLC, we sought to evaluate exarafenib’s therapeutic potential beyond BRAF-mutated cancers." (PMID 41282105, 2025). "Targeted therapies against BRAF mutations have significantly transformed the clinical management of patients with BRAF-mutant cancers." (PMID 40332392, 2025). "While there are approved targeted therapies for BRAF Class I mutants, there are no approved targeted therapy strategies for Class II and Class III BRAF mutated cancers." (PMID 41282105, 2025). "This study focuses on the role of a genetic mutation, BRAF V600E, and its allele frequency (the proportion of mutated DNA) in predicting the aggressiveness of these cancers." (PMID 40805249, 2025). "The earliest recorded basket trial began in 2012 and targeted BRAF V600 mutation-positive cancers (VE-BASKET)." (PMID 41225614, 2025). "Patients with advanced stage BRAF V600-positive cancer have a better prognosis, as this mutation improves the rate of response to personalized treatment." (PMID 40977811, 2025). "The BRAF gene, a main proto-oncogene linked to cancer development and progression, exhibited a mutation rate of 10.67% (16/150 cases) in the present study, aligning with previous findings." (PMID 40949797, 2025). "This underlines the great potential of HDAC inhibitors as promising combination partners for enhanced therapy of advanced and BRAF inhibitor-resistant cancers with activating BRAF mutations." (PMID 39935431, 2025). "A notable case is the vemurafenib basket trial (VE-BASKET), which assessed the efficacy of vemurafenib, a kinase inhibitor, in patients with BRAF V600E mutation-positive Cancers." (PMID 41225614, 2025). "For instance, an on-demand request for BRAF mutational status can be initiated after the confirmation by pathologists of a cancer diagnosis provided by a previously applied classification model." (PMID 40420213, 2025). "BRAF V600E is the most frequent class I mutation in cancer, with BRAF V600 K/D/R mutations being of the same class but less frequent." (PMID 40977811, 2025). "One of the most interesting facts about the anti-cancer role of OIS is the presence of the BRAF V600E mutation in human melanocytic nevi." (PMID 40643463, 2025). "In 7/8 cancers analyzed, the data were consistent with atypical BRAF and concomitant Ras pathway mutations being present in the same clonal population (χ2 tests of independence)." (PMID 39751654, 2025). "BRAF is a well-established oncogene, and its mutation has been identified as a key factor in the development of various cancers." (PMID 40507920, 2025). "These large-scale screens can be used to identify vulnerabilities that are selectively essential for certain mutational subtypes (such as BRAF or KRAS mutated cancers), or to nominate candidate targets selectively required for cancer types of interest." (PMID 40804185, 2025). "Microsatellite stable, BRAF -mutated cancers have poor prognosis in general, whereas MSI-H reverts this." (PMID 39789100, 2025).
cancer (continued). "While tumors with a KRAS mutation are more likely to be associated with recurrence and progression to carcinoma, a BRAF mutation is a significant prognostic factor for a favorable course of the disease." (PMID 40564801, 2025). "This is noteworthy, particularly as some studies have found correlations between BRAF mutations and increased methylation in other carcinoma types." (PMID 40722658, 2025). "KRAS mutations were found in 32% of the FAP samples (24% of LG adenomas and 78% of HG adenomas and carcinomas), while BRAF mutations were found in only 3% of all samples (serrated tumors were excluded from the analysis)." (PMID 41488735, 2025). "In the Cancer Cell Line Encyclopedia, BRAF class 3–mutated NSCLC cell lines showed greater sensitivity to EGFR-TKIs compared with BRAF class 2–mutated and KRAS-mutated lines." (PMID 39637338, 2024). "BRAF’s most common cancer-causing missense mutation, V600E, renders BRAF to be constitutively active as a monomer, leading to abnormal firing of the critical intracellular machinery that governs cell cycle progression." (PMID 38920700, 2024). "This synergistic effect allows for a more comprehensive approach to targeting cancer cells, particularly those with specific genetic mutations like BRAF mutations." (PMID 38473413, 2024). "The same holds true for reports on adult cancer patients in which CSF was analyzed for BRAF mutations." (PMID 38388693, 2024). "The prevalence of BRAF mutations in certain cancer types varies by a range of factors including age." (PMID 38539548, 2024). "Activation of the RAS/MAPK pathway, driven by mutations like HRAS (G12V) and BRAF (V600E), is significant in resistance and metastasis in HH-dependent cancers." (PMID 39568072, 2024). "Cancers arising on the right side were associated with mutations in BRAF; they tend to be larger and frequently show a higher degree of malignancy at diagnosis." (PMID 38409377, 2024). "There are four residues of RAF1 and thirteen residues of BRAF related to cancer mutations at the interface of BRAF–RAF1 complex." (PMID 38216592, 2024). "We also examined the relationship between the BRAF mutation class and co-occurring genomic alterations within specific cancer types." (PMID 38275886, 2024). "Identification of this mutation holds therapeutic significance considering the emergence of targeted therapies against BRAF-mutated cancers." (PMID 39234402, 2024). "Across cancers, BRAF alterations include gain-of-function mutations, copy-number alterations, and structural rearrangements." (PMID 39018217, 2024). "The evolutionary conservation of the BRAF p.V600E mutation highlights the importance of activating the MAPK pathway in cancer." (PMID 38787171, 2024). "Overall, we find distinct co-expression patterns among pathways with respect to BRAF mutation status and age of diagnosis, indicating that the cancer samples are functionally heterogeneous." (PMID 39677786, 2024). "Mutations in the proto-oncogene BRAF are present in 5–10% of human cancers, including malignant melanoma and colorectal, thyroid and lung cancer." (PMID 39335105, 2024). "Our previous results showed that MAPKi promote feedback activation of STAT3 signaling in BRAF-mutated cancer cells." (PMID 38822350, 2024). "The MGPs associated with these target genes appeared to be involved in multiple cancer types with the exception of BRAF-associated MGPs." (PMID 38468344, 2024). "In primary MSI cancers, frequencies of BRAF and RNF43 mutations were lower in younger patients, with correspondingly higher APC frequency (P < 0.05, two-sided Wilcoxon test)." (PMID 39112709, 2024). "In human medicine, BRAF inhibitors have shown significant clinical benefits for patients with BRAFV600E mutated cancer and have been approved by the United States Food and Drug Administration (FDA)." (PMID 39591358, 2024). "Among these mutations, the BRAF V600E mutation accounts for 80% of BRAF mutations identified in human cancers." (PMID 38791222, 2024).
cancer (continued). "BRAF gene encodes a cytoplasmic serine-threonine kinase B-Raf constitutively activated in many cancers of various localization and histogenesis." (PMID 39018206, 2024). "Targeting Shock Heat Protein 2 (SHP2) phosphatase with RMC-4550, a small-molecule allosteric inhibitor, resulted effective in human cancer models with class III BRAF mutations." (PMID 39684685, 2024). "It has previously been reported that Class 1 BRAF mutations commonly occur in cancers that arise in the right colon, whereas Class 2 and 3 non-V600 BRAF mutations more commonly arise in the left colon." (PMID 38275886, 2024). "A major focus of ongoing drug development initiatives is the identification of selective RAF dimer inhibitors against cancers driven by Class II BRAF mutations." (PMID 38770647, 2024). "The B-Raf proto-oncogene, serine/threonine kinase (BRAF)(V600E) mutation is an important driver gene mutation in these cancer types." (PMID 39052013, 2024). "BRAF mutations have been reported to alter gene expression levels in cancer tissues and enhance their association with underlying disease." (PMID 39408810, 2024). "Studies and clinical trials have evaluated FOLFOXIRI in combination with bevacizumab, especially for right-sided and/or BRAF-mutated cancers, focusing on conversion surgery and suitable patients." (PMID 39263130, 2024). "The phenomenon of paradoxical MAPK activation has been extensively investigated in BRAF WT cancer cells, especially in the presence of upstream NRAS mutations." (PMID 38839106, 2024). "Today, it is well known that mutations in BRAF or NRAS are the drivers of up to 70% of human cancers, and therapies that target this pathway have been developed." (PMID 38299666, 2024). "The development of several cancer types is also associated with mutations in the BRAF proto-oncogene." (PMID 39000097, 2024). "Conversely, right-sided cancers are linked to alterations in the BRAF gene, typically present as larger tumors, and often exhibit a more advanced stage of disease upon initial diagnosis." (PMID 38409377, 2024). "Class I BRAF mutations, namely BRAF V600 mutations, account for over 90% of BRAF variations in cancer." (PMID 39529955, 2024). "The high number of BRAF mutations in canine PC and UC showed the possible use of the mutation as a molecular marker in diagnostically challenging cancers." (PMID 39591358, 2024). "There are around 200 identified BRAF mutations across cancer types, and these occur in approximately 5.5% of all cancer in humans." (PMID 38347643, 2024). "Since their discovery in 2002, BRAF mutations have been identified as clear drivers of oncogenesis in several cancer types." (PMID 38539548, 2024). "In the histology samples of the indeterminate nodules, 48 (47.5%) were mutated, being two benign lesions with RAS mutation and in 46 malignant tumors, of which 11 (14.5%) were found to have TERTp mutation, 13 (16.9%) had BRAF, and 22 (29.3%) had RAS mutation." (PMID 38337794, 2024). "Across all three cancer types, the mutational landscape of BRAF Fusions was most similar to tumors with Class 1 BRAF mutations." (PMID 38275886, 2024). "- High fiber, especially from fruits, lowers cancer risk, particularly with genetic factors like BRAF mutations." (PMID 39734671, 2024). "Initial attempts to treat BRAF-mutated cancers by single-agent BRAF inhibitors revealed that tumors rapidly adapt to this therapy by activation of the MEK kinase." (PMID 38966170, 2024). "Since BRAF mutation is highly attributed to cancer, knowledge of the mutational status is certainly helpful when deciding on the degree of lymph node dissection." (PMID 39449865, 2024). "Clinical trials on BRAF-mutant cancers and associated conditions have been the basis on which FDA approvals, new standards of treatment, and novel approaches to research have been made." (PMID 38539548, 2024). "As part of an exploratory analysis, the co-mutational landscape of BRAF-altered cancers was evaluated." (PMID 38791902, 2024).
cancer (continued). "BRAF is a gene encoding the serine/threonine kinase B-Raf, a proto-oncogene found in mutated forms in malignant tumors." (PMID 38730642, 2024). "Here, we developed an approach for the feasibility of accurate CRISPR-Cas12a-based detection of cancer-associated point mutation p.V600E, the most frequently occurring BRAF variant." (PMID 39644903, 2024). "This study represents a significant advancement in the identification of patients suitable for molecular targeted therapy in BRAF V600-associated cancers." (PMID 38333370, 2024). "Amongst all cancers, a wide range of BRAF mutations have been described and can be divided into three classes based on biochemical and signaling aspects though this classification remains controversial." (PMID 39220131, 2024). "This drug, employed for BRAF gene mutation-positive cancers, has shown promising results in reducing or eliminating tumors." (PMID 39654782, 2024). "The five-year Cancer-Specific Survival was significantly worse in cases with mutated BRAF or KRAS, with a p-value of 0.04, and this significance persisted in the multivariate analysis." (PMID 38786299, 2024). "Of note, a previous pan-cancer analysis of 115,000 patients found that non-V600E BRAF mutations accounted for 35% of BRAF mutations, which is lower than the rates of class II and III mutations reported in this study." (PMID 38791902, 2024). "In contrast, all malignant tumors with the BRAF V600E mutation identified in this study were classified as Bethesda III, suggesting a unique mutation profile for these nodules." (PMID 39766147, 2024). "The BRAF gene, located on chromosome 7 in the human genome, encodes for B-raf protein and is well known for its role in human cancer." (PMID 38877523, 2024). "It is also less likely to be directly anti-cancer compared with anti-BRAF plus anti-MEK treatment for patients with BRAF-mutated tumors." (PMID 38539487, 2024). "In 2011, the United States approved Vemurafenib (PLX4032) as the first drug against cancer with BRAF mutation." (PMID 39199653, 2024). "BRAF is one of the most mutated kinases in human cancers, particularly in melanoma, with a mutation rate of 40–50%." (PMID 38791222, 2024). "The truncating BRAF mutations in this sample set have been previously observed in the context of other cancers." (PMID 38711096, 2024). "A comprehensive understanding of the BRAF gene and its mutations is paramount in cancer diagnosis, prognosis, and treatment, underscoring its pivotal role in oncology research and clinical practice." (PMID 39156294, 2024). "SHP2 is a major scaffold protein downstream of numerous receptor tyrosine kinases, promoting RAS/MAPK signaling in cancers with class III BRAF mutations with concomitant RAS mutations." (PMID 38398128, 2024). "The NET formation caused TGF-β activation, which induced a switch in cancer cells from an epithelial-to-mesenchymal phenotype, a state associated with resistance to BRAF inhibitors and chemotherapy." (PMID 38730718, 2024). "This suggests that out of all the BRAF polymorphisms, only BRAF V600E exerts a sufficiently strong cancer-promoting effect to act independently of KRAS mutations." (PMID 39456660, 2024). "Exemplarily we illustrate that both kinases which are activated through cancer patient mutations (BRAF-V600E and MEK1-K57E) bind the respective kinase inhibitor, resulting in a change in the activity conformations." (PMID 39088265, 2024). "Heavy smoking has also been linked to the development of cancers that contain a serrated BRAF mutation." (PMID 39031216, 2024). "This revolutionary study was the first to establish BRAF as a vital signaling factor for the development of the vascular system and, in 2002, the first evidence of an association between BRAF gene mutations and human cancer was described." (PMID 38539548, 2024).
cancer (continued). "Across all cancer types, the relative proportion of non-V600 BRAF mutations (Class 2, 3, and Fusions) was higher in older patients (age 60+) compared to younger patients (age < 60) (p < 0.0001)." (PMID 38275886, 2024). "•BRAF mutations common in various cancers, representing a significant therapeutic target for multiple solid tumors." (PMID 39529955, 2024). "The BRAF proto-oncogene is located on chromosome 7 (7q34), and BRAF gene-activating mutations are present in about 7% of human cancers." (PMID 38203795, 2024). "These predominantly comprise BRAF p.V600E mutations and often meet the diagnostic criteria for high-grade differentiated carcinomas." (PMID 38672067, 2024). "In PDTC and DHGTC, RAS and BRAF mutations are detected at a frequency similar to that in well-differentiated carcinomas." (PMID 38672067, 2024). "Our results illustrated that FAP patients had the highest penetrance, the highest proportion of cancer nodules, BRAF V600E somatic mutation, and multiple primary CRC and extra-colonic cancer, as well as the worst OS and PFS." (PMID 37854294, 2023). "In this study, we evaluate the effectiveness of a proteolysis targeting chimera (PROTAC), SJF-0628, in directing the degradation of mutated BRAF across a diverse panel of cancer cells and determine how these cells respond to the degradation." (PMID 38136350, 2023). "BRAF mutations are detected in ~7–15% of all cancers, and the most common locus of the mutation is at position V600." (PMID 37059834, 2023). "For example, mutations in the BRAF oncogene, commonly found in MM, have also been observed in other cancers." (PMID 37297018, 2023). "Cyclin D1 together with cyclin-dependent kinase (CDK)-4 are key regulators of the G1 phase of the cell cycle, and they are considered therapeutic targets in BRAF-mutated cancers." (PMID 36674794, 2023). "BRAF V600E-mutated cancers exhibited higher T and N scores, as well as higher rates of vascular and perineural invasion compared to non-mutated ones." (PMID 37240418, 2023). "Considering the Afirma Gene Expression Classifier and ThyroSeq genomic classifier are not yet available in China and are expensive, 5 of the most common cancer-associated somatic mutations (BRAF, HRAS, NRAS, KRAS and TERT) were offered in our hospital." (PMID 36737779, 2023). "In the realm of cancer therapy, medications have been created to combat cancers that are fueled by BRAF mutations." (PMID 38021761, 2023). "In the cancers with BRAF mutations in our cohort, 50% were metastatic, whereas the ones with RET fusions were largely metastatic (80%)." (PMID 37317665, 2023). "In patients with BRAF mutated cancer, a molecular mechanism analysis has revealed potential target for RAS/RAF/MAPK inhibitors." (PMID 38105263, 2023). "With respect to the prediction of the BRAF mutation in human cancer, various AI approaches have been described in the literature, and each has its strengths and weaknesses." (PMID 37570213, 2023). "In the realm of therapeutic interventions, RAS/RAF/MAPK inhibitors have emerged as promising targets for addressing BRAF-mutated cancers and other disorders." (PMID 38105263, 2023). "Our findings support the previous studies, which report the significant implication of BRAF in cancer and associate right-sided colon cancer with worse clinical outcomes." (PMID 36673047, 2023). "For example, the Rare Oncology Agnostic Research (ROAR) study evaluated the efficacy of dabrafenib and trametinib in treating rare cancers with the BRAF V600E mutation." (PMID 37185413, 2023). "These BRAF mutations and their impact on protein function are crucial for developing targeted therapies for cancers." (PMID 38021761, 2023).